PDP1 (pyruvate dehydrogenase phosphatase catalytic subunit 1)
Description:
Mitochondrial enzyme that catalyzes the dephosphorylation and concomitant reactivation of the alpha subunit of the E1 component of the pyruvate dehydrogenase complex (PDC), thereby stimulating the conversion of pyruvate into acetyl-CoA.
Synonyms: PDPC 1; PDP; PPM2C; PDH; PPM2A; PDPC
Tractability: PROTAC: ubiquitination databases record sites on it; its protein half-life has been measured.
Gene: Protein-coding gene on chromosome 8 (93,857,788 to 93,926,068, forward strand). Ensembl gene ENSG00000164951.
Subcellular location: Mitochondrion
Subcellular location (Human Protein Atlas): Cytosol; Nucleoplasm; Mitochondria; Vesicles
Pathways (Reactome):
Metabolism: Regulation of pyruvate dehydrogenase (PDH) complex
Gene Ontology:
Molecular function: [pyruvate dehydrogenase (acetyl-transferring)]-phosphatase activity; protein binding; protein serine/threonine phosphatase activity; cation binding
Biological process: peptidyl-threonine dephosphorylation; positive regulation of pyruvate decarboxylation to acetyl-CoA
Cellular component: mitochondrion; mitochondrial matrix; pyruvate dehydrogenase (lipoamide) phosphatase complex
Genetic constraint (gnomAD): Loss-of-function variants: 13 observed, 38.83 expected, observed/expected ratio (o/e) 0.33, 90% interval 0.22 to 0.53. The upper end of that interval is the gene's LOEUF score, 0.53, which puts it in group 2 of 6, group 1 being the genes least tolerant of losing a copy. Missense variants: 544 observed, 687.78 expected, observed/expected ratio (o/e) 0.79, 90% interval 0.74 to 0.85. Synonymous variants: 249 observed, 257.91 expected, observed/expected ratio (o/e) 0.97, 90% interval 0.87 to 1.07.
Homologues: Orthologues: macaque PDP1 (99% identical), chimpanzee PDP1 (99% identical), mouse Pdp1 (98% identical), rabbit PDP1 (98% identical), rat Pdp1 (98% identical), dog PDP1 (98% identical), pig PDP1 (92% identical), tropical clawed frog pdp1 (86% identical), zebrafish pdp1 (72% identical), Drosophila melanogaster Pdp (35% identical), Caenorhabditis elegans pdp-1 (33% identical), Drosophila melanogaster CG10376 (15% identical). Paralogues in human: PDP2 (48% identical), PPM1B (17% identical), PPM1M (17% identical), PPM1A (16% identical), PPM1E (16% identical), PPM1H (16% identical), PPM1N (16% identical), PPM1F (16% identical), PPM1G (16% identical), PPM1J (15% identical), PPM1K (15% identical), TAB1 (14% identical), and 4 more.
Diseases named in the same sentence as PDP1 in open-access papers:
PDP1 is named in the same sentence as 150 diseases in open-access papers, as found by Europe PMC text mining. Sharing a sentence is not in itself a finding about the gene and the disease. The quoted sentences say what the papers report.
breast cancer (27 papers, 2008 to 2025). A primary or metastatic malignant neoplasm involving the breast. "PDP1 gene is overexpressed in breast cancer tissues and correlates with poor prognosis, Validation through in vivo and in vitro experiments further confirmed that PDP1 contributes to cancer progression by regulating STAT3 phosphorylation levels." (PMID 40746885, 2025). "In vitro studies revealed that increased levels of PDP1 expression reduced the invasion of CD8+ T cells in breast cancer." (PMID 40746885, 2025). "In our unpublished previous study, PDP1 has been found to be upregulated in breast cancer compared to normal tissues." (PMID 40337509, 2025). "The results revealed a significant upregulation of PDP1 expression in breast cancer samples across all three datasets." (PMID 40337509, 2025). "Bioinformatics data analysis found that PDP1 is highly expressed in breast cancer tissues, and PDP1 expression is positively correlated with N-stage and negatively correlated with CD8+ T cell invasion." (PMID 40746885, 2025). "By bioinformatics analysis, validation of PDP1 expression in breast cancer samples versus normal samples was conducted using the GSE42568, GSE45827, and GSE61594 datasets." (PMID 40337509, 2025). "It was found that the high expression of PDP1 was negatively correlated with the invasion of CD8T cells in breast cancer." (PMID 35120331, 2022). "We detected the expression of PDP1 in 70 cases of breast cancer and 20 cases of adjacent tissues by Immunohistochemical staining." (PMID 35120331, 2022). "High expression of PDP1 is negatively correlated with CD8+ T cell infiltration in breast cancer." (PMID 40746885, 2025). "Additionally, in comparison to normal samples, breast cancer exhibited a relatively higher expression of PDP1, as illustrated by representative immunohistochemistry (IHC) images." (PMID 40337509, 2025). "Preliminary research shows that the PDP1 gene is overexpressed in breast cancer tissues and correlates with poor prognosis, Validation through in vivo and in vitro experiments further confirmed that PDP1 contributes to cancer progression by regulating STAT3 phosphorylation levels." (PMID 40746885, 2025). "Breast cancer samples from the GSE21653 dataset were divided into HPG and LPG based on the median expression values of the PDP1 (6.49)." (PMID 40337509, 2025). "In breast cancer patients from the TCGA-BRCA dataset with complete clinical survival information, a univariate Cox regression analysis was conducted using the expression values of 15 PDP1-related differentially expressed FRGs as continuous variables." (PMID 40337509, 2025).
lactic acidosis (22 papers, 2009 to 2025). Metabolic acidosis characterized by the accumulation of lactate in the body. "A deficiency of PDP1 has been reported to cause severe exercise intolerance, lactic acidosis, and mild developmental delay." (PMID 40491447, 2025). "The group reported a homozygous mutation within the PDP1 gene in the fibroblast of a female patient showing symptoms of lactic acidosis and mild truncal hypotonia." (PMID 40491447, 2025).
colorectal cancer (16 papers, 2019 to 2026). A primary or metastatic malignant neoplasm that affects the colon or rectum. "Increased levels of PDP1 in KRAS mutant colorectal cancer (CRC) cells and tissues are linked to a worse prognosis." (PMID 40746885, 2025). "PDP1 is highly expressed in a variety of cancers, usually related to bad prognosis, such as colorectal cancer and BC." (PMID 40337509, 2025). "Both in vivo and in vitro studies show that PDP1 enhances the malignancy of KRAS mutant colorectal cancer cells." (PMID 40746885, 2025). "Kyoto Encyclopedia of Genes and Genomes (KEGG) analysis showed that in the patients with high PDP1 expression, terms of glycosphingolipid biosynthesis lacto and neolacto series, allograft rejection, graft versus host disease, and colorectal cancer were mainly enriched in." (PMID 36276992, 2022). "Shi and colleagues demonstrated that the PDP1-PDH-histone acetylation retrograde signaling activated by mitochondrial dysfunction could significantly increase the radioresistance in colorectal cancer." (PMID 36276992, 2022). "Following resveratrol intervention, a decrease in PDH activity has been observed in Caco-2 and HCT116 colorectal cancer cell lines, indicating that resveratrol-induced glycolytic reprogramming may occur through the modulation of PDP1 gene expression." (PMID 39330497, 2024).
ovarian carcinoma (11 papers, 2016 to 2026). A malignant neoplasm originating from the surface ovarian epithelium. "PDP1 promotes the proliferation, invasion, and migration of ovarian cancer cells and is associated with poor prognosis." (PMID 40746885, 2025). "Bioinformatics analysis of ovarian cancer data indicates a high expression of PDP1 in ovarian cancer tissues." (PMID 40746885, 2025). "PDP1 enhances the proliferation, invasion, and migration of ovarian cancer cells." (PMID 40746885, 2025). "To explore potential drugs targeting patients in the GMPI‐high group, we collected four ovarian cancer samples and calculated GMPI for each sample with the following formula: GMPI = 0.090* KIAA0100 + 0.043* ANKRD27 + 0.215* OPA3 + 0.171* NUMBL + 0.314* PDP1–0.233*SLC7A11–0.007* TRMT112." (PMID 38506093, 2024).
pancreatic cancer (9 papers, 2021 to 2025). "In pancreatic cancer tissue studies, it was found that PDP1 is highly expressed and is associated with poor patient prognosis." (PMID 40746885, 2025). "PDP1 overexpression has been reported to be present in human prostate and pancreatic cancers, promoting cell proliferation and tumor growth." (PMID 40367233, 2025). "PDP1 increases ATP production and promotes pancreatic cancer cell proliferation, invasion, and migration." (PMID 40746885, 2025). "Subsequently, risk score distribution and expression patterns of PDP1, DLAT, DBT, LIAS and LITP1 in pancreatic cancer samples were analyzed." (PMID 40367233, 2025). "hsa-miRNA-135b-5p positively regulates PDP1 in low-grade gliomas, while negatively regulating PDP1 in head and neck squamous cell carcinoma and pancreatic cancer." (PMID 40746885, 2025). "In pancreatic cancer, PDP1 promotes cancer proliferation and invasion by regulating the MAPK/mTOR signaling pathway." (PMID 38831425, 2024). "In pancreatic cancer, Li and colleagues found that PDP1 promotes pancreatic cancer proliferation and invasion through regulating the MAPK/mTOR signaling pathway." (PMID 36276992, 2022). "PDP1 promotes the proliferation, invasion, and migration of pancreatic cancer cells." (PMID 40746885, 2025). "PDP1, DLAT, DBT, LIAS and LITP1 were determined to be markedly higher at mRNA levels in pancreatic cancer Capan-1, CFPAC-1, PANC-1, MIA PaCa-2, and COLO357 cells than in normal HPDE6-C7." (PMID 40367233, 2025).
colon cancer (8 papers, 2008 to 2024). "The cancer-promoting effect of PDP1 on cancer cells was observed in multiple cancers, including colon cancer, prostate cancer, and nonsolid tumor." (PMID 36276992, 2022).
glioblastoma (8 papers, 2015 to 2025). The most malignant astrocytic tumor (WHO grade IV). "Research using a mouse model of glioblastoma indicated that restoring PDP1 expression reduces tumorigenicity." (PMID 40746885, 2025). "The Cancer Genome Atlas (TCGA) database indicates that PDP1 levels are significantly suppressed in glioblastoma." (PMID 40746885, 2025).
prostate carcinoma (8 papers, 2015 to 2025). A carcinoma that arises from epithelial cells of the prostate gland. "In prostate cancer tissues, the PDP1 protein is highly expressed, and elevated PDP1 levels are associated with enhanced mitochondrial oxygen consumption from glucose and glutamine." (PMID 40746885, 2025). "High expression of PDP1 is associated with a poor prognosis in prostate cancer." (PMID 40746885, 2025). "A recent study showed that the expression of PDP1 was elevated in prostate cancer, in which ectopic expression of PDP1 promoted cancer growth and progression." (PMID 32782783, 2020). "Overexpression of PDP1 was also found in human prostate cancer and could promote cell proliferation and tumor growth." (PMID 32782783, 2020). "Moreover, Chen and colleagues found that PDP1 was overexpressed in prostate cancer and could sustain prostate tumorigenesis by controlling lipid biosynthesis." (PMID 36276992, 2022). "Correlation between clinical and pathological variables and PDHA1, PDP1 and PDP2 protein expression in prostate cancer." (PMID 35692804, 2022).
lung carcinoma (6 papers, 2020 to 2025). "In lung cancer cells (H1299), increased lysine acetylation of PDP1 results in decreased phosphatase activity, which suggests that this acetylation inhibits PDP1’s function." (PMID 40746885, 2025).
glioma (5 papers, 2021 to 2025). A benign or malignant brain and spinal cord tumor that arises from glial cells (astrocytes, oligodendrocytes, ependymal cells). "Single-cell transcriptomic analysis indicates that hsa-miRNA-655-3p positively regulates PDP1 specifically in low-grade gliomas." (PMID 40746885, 2025).
acute myeloid leukemia (4 papers, 2023 to 2025). Acute myeloid leukemia (AML) is a group of neoplasms arising from precursor cells committed to the myeloid cell-line differentiation. "In acute myeloid leukemia (AML), the increase d expression of PDP1 is associated with metabolic reprogramming following FLT3 inhibition." (PMID 40337509, 2025). "Additionally, in FLT3-ITD-positive acute myeloid leukemia (AML) cells, PDP1 facilitates cellular respiration, even under hypoxic conditions." (PMID 39776803, 2025). "Regardless of PDP1’s function, its role in maintaining acute myeloid leukemia cell survival depends on its ability to enhance the OXPHOS activity." (PMID 40746885, 2025).
osteoarthritis (3 papers, 2022 to 2024). A noninflammatory degenerative joint disease occurring chiefly in older persons, characterized by degeneration of the articular cartilage, hypertrophy of bone at the margins and changes in the synovial membrane. "Research has shown that miR-18a-3p improves cartilage matrix remodeling and suppresses inflammation in osteoarthritis by targeting PDP1." (PMID 38831425, 2024).
osteosarcoma (3 papers, 2020 to 2024). A usually aggressive malignant bone-forming mesenchymal neoplasm, predominantly affecting adolescents and young adults. "Additionally, PDP1 is associated with osteosarcoma progression, patient prognosis, and chemosensitivity, making it a potential biomarker for osteosarcoma." (PMID 38831425, 2024).
viral infection (3 papers, 2023 to 2025). "Therefore, while PDK1- and PDP1-transduced CD8+ T cells mounted better responses in the virus infection model, their antitumor responses were compromised." (PMID 40857407, 2025). "Contrary to expectations, we found either enforced PDK1 or PDP1 expression resulted in enhanced CD8+ T cell metabolic capacity and increased primary and secondary responses in a virus infection model." (PMID 40857407, 2025). "To test the role of enforced PDK1 or PDP1 expression on the T cell response in vivo, we elected to use the MHV-68 model system, a persistent virus infection model that induces a potent CD8+ T cell response does not subject T cells to exhaustion." (PMID 40857407, 2025).
leukemia (2 papers, 2023 to 2025). A malignant (clonal) hematologic disorder, involving hematopoietic stem cells and characterized by the presence of primitive or atypical myeloid or lymphoid cells in the bone marrow and the blood. "Studies identified PDP1 as a modulator of drug resistance in the Fms-like tyrosine kinase 3- internal tandem duplications (FLT3-ITDs) positive leukemia." (PMID 40491447, 2025). "Previous work by us and others highlighted the importance of the RAS pathway in the oncogenic signaling and transformation of FLT3-ITD-positive leukemia and in this study, we extend this to its role in maintaining PDP1-driven OXPHOS." (PMID 37935978, 2023). "In line with the well-established role of metabolism in drug sensitivity in AML and considering the central metabolic functions of PDP1, we aimed to investigate the relevance of PDP1 as a modulator of leukemia response to FLT3 inhibitors." (PMID 37935978, 2023). "This study found elevated expression of phosphorylated Tyr-94 in the primary leukemia cells isolated from leukemia patients compared to normal cells from healthy individuals suggesting a correlation between tyrosine phosphorylation of PDP1 and the cancer pathophysiology." (PMID 40491447, 2025). "PDP1 may thus be a potential therapeutic target to revert the sensitivity of drug resistant tumor cells and leukemia treatment." (PMID 40491447, 2025). "To functionally assess the role of PDP1 in leukemia development in vivo, we transplanted (FLT3-ITD-positive) Molm13 cells transduced with either non-targeting control (NTC) or PDP1 shRNA expression vectors into immunocompromised NOD/SCID interleukin-2 receptor gamma knockout (NSG) mice." (PMID 37935978, 2023). "In the initial experiments, we showed that PDP1 expression is enhanced in FLT3-ITD-dependent leukemia cells, and thus it seemed at first sight surprising that FLT3 inhibition enhanced PDP1 expression in these cells even further." (PMID 37935978, 2023). "In order to show that PDP1 dependency is indeed due to its metabolic function, we made use of another model, where we engineered an FLT3-ITD-expressing leukemia cell line that proliferates independently of mitochondrial energy production (Rho Zero cells)." (PMID 37935978, 2023).
myeloproliferative disorder (2 papers, 2016 to 2022). A clonal hematopoietic stem cell disorder, characterized by proliferation in the bone marrow of one or more of the myeloid (i.e., granulocytic, erythroid, megakaryocytic, and mast cell) lineages. "PDP1 overexpression leads to exhaustion of hematopoietic stem cells to increase the occurrence of myeloproliferative disorder." (PMID 35148687, 2022). "This analysis focused on genes (Srpk2, Hes1, Mtor, Pdp1, Meis1, Gfi1, Foxo3, Stra13, Hif1α, and Cebpε) involved in HSC proliferation; maintenance of quiescence, growth, and stem cell exhaustion; and development of myeloproliferative disorder in young and geriatric mice." (PMID 27366154, 2016).
B cell lymphoma (1 paper, 2025). "CD8+ T cells transduced with PDK1 or PDP1 show compromised protection against mouse B cell lymphoma, which is rescued by glutamine and acetate supplementation." (PMID 40857407, 2025). "To test this, we administered daily glutamine and sodium acetate supplements intraperitoneally to EμMyc B cell lymphoma–bearing mice that received CD8+ T cells transduced with EV, PDK1, or PDP1." (PMID 40857407, 2025).
Barth syndrome (1 paper, 2025). Barth syndrome (BTHS) is an inborn error of phospholipid metabolism characterized by dilated cardiomyopathy (DCM), skeletal myopathy, neutropenia, growth delay and organic aciduria. "The table summarizes key differences between PDP1 and PDP2, including their expression patterns across tissues, regulatory features, and known associations with disease states such as cancer, traumatic brain injury (TBI), cardiomyogenesis defects, and Barth syndrome." (PMID 40491447, 2025).
lymphoma (1 paper, 2025). A malignant (clonal) proliferation of B- lymphocytes or T- lymphocytes which involves the lymph nodes, bone marrow and/or extranodal sites. "Therefore, EGR1-mediated PDP1 activation increases intracellular ATP production, providing sufficient energy to enhance the proliferation and survival of ibrutinib-resistant lymphoma cells." (PMID 40746885, 2025).
osteoporosis (1 paper, 2024). A condition of reduced bone mass, with decreased cortical thickness and a decrease in the number and size of the trabeculae of cancellous bone (but normal chemical composition), resulting in increased fracture incidence. "Given its role in multiple diseases, PDP1 is considered a potential diagnostic target for osteoporosis in sarcopenic patients." (PMID 38831425, 2024). "Our study systematically identified seven candidate hub genes (PDP1, ALS2CL, VLDLR, PLEKHA6, PPP1CB, MOSPD2, and METTL9) through a combination of various bioinformatics analyses and machine learning algorithms, and provided a nomogram for diagnosing sarcopenia associated with osteoporosis." (PMID 38831425, 2024). "A notable finding is the identification of 7 key candidate genes (PDP1, ALS2CL, VLDLR, PLEKHA6, PPP1CB, MOSPD2, and METTL9), and the development of a nomogram for diagnosing osteoporosis in sarcopenia patients." (PMID 38831425, 2024). "We identified 7 candidate hub genes (PDP1, ALS2CL, VLDLR, PLEKHA6, PPP1CB, MOSPD2, METTL9) and constructed column line plots for osteoporosis combined with sarcopenia." (PMID 38831425, 2024).
pancreatic adenocarcinoma (1 paper, 2020). "Human pyruvate dehydrogenase phosphatase 1 (PDP1) plays an important physiological role in energy metabolism; however, its expression and function in human pancreatic adenocarcinoma (PDAC) remain unknown." (PMID 32782783, 2020).
periodontitis (1 paper, 2024). An acute or chronic inflammatory process that affects the tissues that surround and support the teeth. "MR analysis corroborated the inferences drawn from scRNA-seq, identifying ten causal gene markers associated with periodontitis, including LIMA1, PEA15, TMEM158, CMTM6, PDP1, FFAR4, VAC14, and ENHO." (PMID 39830509, 2024).